UGT1A1 (UDP glucuronosyltransferase family 1 member A1)
Diseases named in the same sentence as UGT1A1 in open-access papers (continued):
Sharing a sentence is not in itself a finding about the gene and the disease.
neutropenia (continued). "In the present study, an association was demonstrated between the incidence of G4 neutropenia and the UGT1A1*6/*28 or *6/*6 genotype in Japanese patients with gynecological cancers who received low-dose CPT-11 therapy." (PMID 24932285, 2014). "Multivariate analysis demonstrated the involvement of only UGT1A1*6/*28 and *6/*6 as a risk factor for the occurrence of G4 neutropenia in patients with gynecological cancers who received low-dose CPT-11." (PMID 24932285, 2014). "In parallel with this advance in the USA, clinical relevance to severe neutropenia of UGT1A1*6 [211G>A(G71R)], another low-activity allele detected specifically in East Asians, as well as *28, was demonstrated in several studies on Asian patients." (PMID 25127363, 2014). "Concordantly, individuals with one or more UGT1A1*28 alleles experience higher risk of neutropenia from irinotecan treatment at doses higher than 250 mg/m2." (PMID 23382909, 2013). "SN-38 is inactivated by the enzyme UGT1A1 by glucuronidation, so that patients with UGT1A1 polymorphism are likely to develop severe irinotecan-related toxicities such as diarrhea and neutropenia." (PMID 21861888, 2011). "It is noteworthy that 33.3% of patients homozygous for the UGT1A1*28 allele developed severe neutropenia and diarrhoea at the same time, whereas only 1.8% of UGT1A1*1/*1 and 5.2% of UGT1A1*1/*28 patients did so (OR=12.38, 95% CI=2.38–54.18, P<0.0001)." (PMID 20628391, 2010). "UGT1A1*28 was specifically associated with neutropenia at the end of treatment and with diarrhoea after first cycle of chemotherapy." (PMID 20628391, 2010). "Several studies have demonstrated that UGT1A1 polymorphisms are associated with an increased risk for neutropenia." (PMID 19639031, 2008). "In 177 Japanese patients treated with irinotecan-including chemotherapy, a homozygous or double heterozygous genotype for UGT1A1*6 and UGT1A1*28 (*6/*6, *28/*28 or *6/*28) was significantly associated with severe neutropenia." (PMID 18985035, 2008). "It highlights individuals with specific UGT1A1 genetic variations—such as double heterozygotes for *6 and *28, or homozygotes for *6 or *28, are at risk of delayed SN-38 metabolism, which can lead to serious adverse drug reactions such as neutropenia." (PMID 40432911, 2025). "Given its higher prevalence in Asian populations, the UGT1A1*6 polymorphism may serve as a better predictor of irinotecan-related neutropenia in the Thai population." (PMID 41385496, 2025). "Similarly, UGT1A1 polymorphisms, particularly UGT1A1*28, impair irinotecan metabolism and raise the risk of neutropenia and diarrhea, warranting dose reductions for homozygous carriers." (PMID 40805233, 2025). "Moreover, after applying the Bonferroni correction, the UGT1A1 phenotype remained significantly associated with all-grade neutropenia in the first cycle and severe neutropenia in the second cycle." (PMID 41385496, 2025). "In addition, it recommends the close monitoring of patients with UGT1A1*28 or *6 alleles for neutropenia during and after treatment with CAMPTOSAR®." (PMID 40430836, 2025). "Therefore, patients homozygous or heterozygous for the UGT1A1*28 or *37 alleles commonly develop severe dose-limiting neutropenia and late diarrhea." (PMID 40430836, 2025). "Additionally, polymorphisms of the UGT1A1 gene (e.g., UGT1A1*6 and UGT1A1*28), have been associated with a higher risk of severe neutropenia and irinotecan-induced delayed diarrhea." (PMID 39204392, 2024). "However, sixteen patients (28%) were tested for UGT1A1 polymorphisms; UGT1A1 variants was found in 4 patients, two of them experienced neutropenia (grade 3) and one patient experienced hypertransaminasemia (grade 4) and alopecia." (PMID 38595817, 2024). "Interestingly, the presence of homozygosity of the UGT1A1 *28 allele (*28/*28; 9.3% of patients) was associated with an increased risk for neutropenia with higher all-grade neutropenia in homozygous patients compared with heterozygous or wild-type patients." (PMID 39796075, 2024).
neutropenia (continued). "Interestingly, Homozygous patients with the UGT1A1*28 allele were found to have a heightened susceptibility to neutropenia when administered SG, as indicated by a higher incidence of all-grade neutropenia compared to heterozygous or wild-type individuals." (PMID 39135109, 2024). "SN-38 is metabolized by uridine diphosphate-glucuronosyltransferase family 1 member A1 (UGT1A1)–mediated glucuronidation, and the risk of developing neutropenia is increased in patients homozygous for the UGT1A1*28 allele compared with heterozygous or wild-type patients." (PMID 37855848, 2023). "It is suggested that not only patients with UGT1A1 double variants but also patients with UGT1A1*1/*28 or *1/*6 may be prone to neutropenia." (PMID 36836140, 2023). "Multifactorial regression analysis showed that after adjusting the cofounders, UGT1A1*28 remained as an independent risk factor for vomiting and mucositis, and UGT1A1*6 was the independent risk factor for the severity of vomiting and degree of neutropenia." (PMID 35340156, 2022). "Despite the dose reduction we applied, we observed a numerically higher rate of severe neutropenia in patients with homozygous polymorphisms in the UGT1A1 gene (*28/*28) when compared to heterozygous or wild-type genotypes (*1/*1 or *1/*28 allele carriers) with and without dose reduction." (PMID 35207692, 2022). "Among white people, risk of neutropenia was high in patients with UGT1A1*28 genotype mutations." (PMID 35340156, 2022). "Some of these isoforms have been shown to have clinical significance for SN-38 glucuronidation and irinotecan-related toxicity; in particular, the low-activity UGT1A1 isoform, UGT1A1*28, is strongly associated with irinotecan-induced neutropenia, especially in Western populations." (PMID 36239106, 2022). "For instance, with irinotecan treatment, up to 50% of Western patients with the UGT1A1*28 allele suffered from severe neutropenia, and these findings led to the recommendation to consider a reduced initial dose for patients known to be homozygous for the UGT1A1*28 allele." (PMID 36239106, 2022). "Individuals with 1 or 2 alleles of UGT1A1*6 have a higher risk of irinotecan-induced neutropenia." (PMID 35176049, 2022). "Eleven patients (39.2%) carrying the homozygous UGT1A1*28 allele developed grade ≥ 3 neutropenia despite upfront reduced irinotecan doses, as compared to 19.6% of heterozygous or wild-type patients treated with full doses (ORvs*28/*28 genotype = 0.38; 95% CI: 0.14–1.03; p = 0.058)." (PMID 35207692, 2022). "However, among Chinese gastric cancer patients treated with irinotecan, only the UGT1A1*6 variant was related to severe neutropenia." (PMID 36239106, 2022). "Incidence of severe neutropenia was related to irinotecan doses and UGT1A1 polymorphisms." (PMID 35207692, 2022). "Corresponding to previous studies, simulations with the PK/PD model indicated a dose-dependent risk of severe neutropenia following irinotecan therapy, which was considerably increased in patients with reduced UGT1A1 activity (grade 4 neutropenia in wild-type/poor metabolizers: 14%/21%)." (PMID 33733372, 2021). "Of the 84% of patients who received sacituzumab govitecan, and had UGT1A1 genotype results, the incidence of grade 4 neutropenia was 26% in patients homozygous for the UGT1A1*28 allele, 13% in patients heterozygous for the UGT1A1*28 allele, and 11% in patients homozygous for the wild type allele." (PMID 34834563, 2021). "UGT1A1*6G/A and A/A type could increase the risk of grade 3~4 diarrhea and neutropenia (p = 0.001; p = 0.017)." (PMID 32264830, 2020). "Homozygous UGT1A1*6 is also associated with severe neutropenia." (PMID 32666389, 2020). "In addition, UGT1A1*6 was significantly associated with grade 1–4 and severe neutropenia (grade 3–4) (OR 20.3, 95% CI 4.3–95.6; P < 0.001, and OR 4, 95% CI 1.2–13; P < 0.026, respectively)." (PMID 32778670, 2020).
neutropenia (continued). "However, UGT1A1 genotype was associated with an increased risk of grade 1–4 and severe neutropenia at the first and second cycle." (PMID 32778670, 2020). "Similarly, UGT1A1*6 was significantly associated with grade 1–4 and severe neutropenia at the first and second cycles in this study." (PMID 32778670, 2020). "Moreover, Guangxi Zhuang patients with UGT1A1*6 mutations had a higher risk of 3~4 grade diarrhea and neutropenia those with wild-type." (PMID 32264830, 2020). "However, in Asian populations, the UGT1A1*6 variant is more common and appears to be a more accurate predictor of neutropenia (all irinotecan doses) and diarrhea than the UGT1A1*28 variant." (PMID 32758288, 2020). "The UGT1A1*28 allele is the most important risk factor for severe neutropenia or diarrhea." (PMID 32778670, 2020). "In subgroup analysis, UGT1A1*6 polymorphism still increases the risk of severe neutropenia." (PMID 32936306, 2020). "Similarly, UGT1A1*6 was significantly associated with grade 1–4 (OR 20.3, 95% CI 4.3–95.6; P < 0.001) and severe neutropenia (OR 12.5, 95% CI 3.4–45.7; P < 0.001)." (PMID 32778670, 2020). "It remains unknown whether there is an association between UGT1A1 gene polymorphisms (UGT1A1∗28, UGT1A1∗6) and irinotecan-induced diarrhea and neutropenia in Japanese children." (PMID 31876708, 2019). "Consistently, genotyping analyses of patients treated with 5-FU and irinotecan within the randomized phase III Nordic IV trial and the randomized phase III TRIBE trial, confirmed the association between the UGT1A1*28/*28 genotype and higher risk of neutropenia." (PMID 34532592, 2018). "A UGT1A1 *28 or UGT1A1 *6 phenotype may increase the risk of neutropenia owing to higher SN-38 exposure by decreasing the UGT1A1 metabolic clearance, as found in various clinical studies." (PMID 28397089, 2017). "The UGT1A1 gene is responsible for the metabolism of SN-38, which is an active metabolite of irinotecan, and variants of UGT1A1 have been reported to intensify myelosuppression, such as severe neutropenia." (PMID 29340058, 2017). "Finally, the results showed that UGT1A1*6 and UGT1A1*28 had an association with irinotecan-induced severe neutropenia." (PMID 28637434, 2017). "However, one subject with heterozygous mutation in both UGT1A1*6 and UGT1A1*28 had the highest dose-normalized AUC of SN-38 and experienced grade IV neutropenia and grade III diarrhea." (PMID 27871319, 2016). "Moreover, in the Asian population, the UGT1A1 ∗6 variant was also identified and was associated with severe neutropenia and diarrhea." (PMID 27563673, 2016). "Since UGT1A1*28 homozygous individuals have only 35% of the activity in wild-type UGT1A1 individuals and metabolize irinotecan more slowly, cancer patients with the UGT1A1*28/*28 genotype are at an increased risk of high-grade neutropenia and/or diarrhea while being treated with irinotecan." (PMID 26820647, 2016). "UGT1A1 deficiency, caused by some polymorphisms, results in SN-38 accumulation, causing irinotecan-related toxicity, which includes diarrhea, dehydration and neutropenia." (PMID 27563673, 2016). "We studied the relation between the safety of irinotecan-based regimens and UGT1A1 genotype and developed a nomogram to predict the risk of irinotecan-induced severe neutropenia in 1312 advanced colorectal cancer patients registered in a prospective observational study." (PMID 25880011, 2015). "Genetic polymorphisms in UGT1A1, such as UGT1A1*28 in Caucasians and Asians and UGT1A1*6 only in Asians, contribute to interpatient variability in the pharmacokinetics and toxicities of irinotecan, particularly severe neutropenia." (PMID 25880011, 2015). "In 2008, the Ministry of Health, Labour, and Welfare of Japan likewise recommended that the package insert be revised to warn of the risk of severe irinotecan-related neutropenia in Japanese patients who are either homozygous for UGT1A1*6 or UGT1A1*28 or heterozygous for both UGT1A1*6 and UGT1A1*28." (PMID 25880011, 2015).
neutropenia (continued). "In addition, the UGT1A1*6/*28 genotype has also been reported to increase the risk of CPT-11-induced G3/4 neutropenia in Japanese patients with colorectal or lung cancer, which agrees with the data from the present study on this genotype." (PMID 24932285, 2014). "Multivariate logistic regression analysis was then used to confirm the significant association between the presence of the homozygous variant UGT1A1 genotype (*6/*28 or *6/*6) and the risk of G4 neutropenia (P=0.029; odds ratio, 6.90; 95% confidence interval, 1.22–38.99)." (PMID 24932285, 2014). "Since 2005, the US Food and Drug Administration (FDA) has recommended that a reduced initial dose of irinotecan should be considered for patients known to be homozygous for the UGT1A1*28 allele, because they are at increased risk for neutropenia following irinotecan treatment." (PMID 24834123, 2014). "However, associations between the occurrence of severe neutropenia and the UGT1A1*28 variant in these cases is not well known." (PMID 24932285, 2014). "A decrease in the level of functional UGT1A1 enzyme reduces a person’s ability to metabolize SN-38 to an inactive form, and is also associated with a higher risk of adverse side effects, like neutropenia and diarrhea caused by high levels or prolonged exposure to the active form." (PMID 24759962, 2013). "Indeed, homozygosity for UGT1A1*28 has been clearly identified as a risk factor for developing severe irinotecan-induced neutropenia, while heterozygous patients seem at intermediate risk." (PMID 22045187, 2011). "However, a meta-analysis demonstrated that the risk of grade 3–4 neutropenia in patients with a UGT1A1*28/*28 genotype was correlated with the dose of irinotecan." (PMID 24212636, 2011). "Our study thus confirms the importance of the pre-therapeutic determination of the UGT1A1 genotype for predicting irinotecan toxicity, and indicates that heterozygous patients may be also at increased risk for neutropoenia." (PMID 18797458, 2008). "Furthermore, investigating cases with UGT1A1 homozygous or double heterozygous polymorphisms associated with neutropenia might provide valuable insights into the relationship between neutropenia and antitumor efficacy." (PMID 39870769, 2025). "However, both UGT1A1-6 and UGT1A1-28 variants were significantly linked to severe neutropenia." (PMID 40432911, 2025). "Finally, the variant in the UDP-glucuronosyltransferase 1 gene (UGT1A1) rs4148323, correlated with irinotecan neutropenia, exhibits the highest MAF in East Asian (MAF = 0.136) and Chilean (MAF = 0.025) populations, distinguishing them from other investigated populations." (PMID 38675222, 2024). "In addition, considering UGT1A1 heterozygosity as a risk factor for neutropenia may allow for a more accurate evaluation of the safety of nal-IRI-containing chemotherapy in future clinical trials." (PMID 36836140, 2023). "In addition, although there is some literature on the relationship between specific factors such as UGT1A1 polymorphism and severe neutropenia for mFOLFIRINOX10, few studies until now have focused on the risk factors for severe neutropenia in patients treated with mFOLFIRINOX." (PMID 36114233, 2022). "Statistical analysis showed that UGT1A1*6 G/A + A/A patients had a higher risk of grade 3~4 diarrhea as compared to G/G patients, with statistically significant difference (χ2 = 11.364, p = 0.001), and also a higher risk of grade 3~4 neutropenia as compared to G/G patients (χ2 = 5.727, p = 0.017)." (PMID 32264830, 2020). "UGT1A1 ∗28/ ∗28 genotype was associated with more than fourfold (OR, 4.79; 95% CI, 3.28–7.01; p < 0.00001) and threefold (OR, 3.44; 95% CI, 2.45–4.82; p < 0.00001) increases in the risk of neutropenia when compared with wild type and with at least one UGT1A1 ∗1 allele, respectively." (PMID 27563673, 2016).
neutropenia (continued). "We prospectively studied the relation between the UGT1A1 genotype and the safety of irinotecan-based regimens in Japanese patients with advanced colorectal cancer, and then constructed a nomogram for predicting the risk of severe neutropenia in the first treatment cycle." (PMID 25880011, 2015). "Despite the absence of significant association with the glucuronidation rate of SN-38, the UGT1A1 polymorphism appeared to be significantly associated with irinotecan toxicity, the patients having at least one variant allele being at increased risk of neutropoenia." (PMID 18797458, 2008). "UGT1A1*6/*6 homozygous subjects had a higher incidence of grade ≥ 3 neutropenia (100%) and anemia (66.7%) in comparison with wild‐type UGT1A1 subjects (52.6% and 10.5%, respectively) – this data was only mentioned in the discussion." (PMID 40936312, 2026). "In the same trial, women with UGT1A1*28/*28 genotype vs. those with 1/*28 and *1/*1 genotypes had higher rates of grade ≥ 3 SG‐related neutropenia, febrile neutropenia, anemia and diarrhea." (PMID 40936312, 2026). "The OR for severe (≥ 3 grade) neutropenia was 2.31 (95% CI: 1.33–4.03) in UGT1A1*28/*28 in comparison with UGT1A1 wild‐type individuals (moderate heterogeneity, I2 = 34%)." (PMID 40936312, 2026). "Used together with irinotecan, SCO-101 led to increased neutropenia due to SCO-101-mediated UGT1A1-inhibition and potentiation of irinotecan." (PMID 40272619, 2025). "Studies have reported that routine UGT1A1 testing is cost effective, reducing the incidence of severe neutropenia and hospitalization costs, especially in patients receiving high-dose irinotecan or those undergoing dose escalation." (PMID 40149251, 2025). "One well-known genetic variant is UGT1A1*28, the occurance of neutropenia and CID resulting from elevated SN-38 in response to gene exposure following irinotecan dosing as affected by UGT1A1*6 and UGT1A1*28 allele conditions." (PMID 40056250, 2025). "In an exploratory safety analysis, patients with the UGT1A1 *28/*28 genotype experienced higher rates of grade ≥3 neutropenia, febrile neutropenia, anemia, and diarrhea compared to those with other genotypes." (PMID 40149251, 2025). "Patients with reduced UGT1A1 activity, particularly those homozygous for UGT1A128 (7/7 genotype), are at a significantly higher risk of developing severe (grade 3 or 4) neutropenia compared to those with the 6/6 or 6/7 genotypes." (PMID 40149251, 2025). "In particular, patients with the UGT1A1*6 wild-type (GG) have a lower incidence of grade 0–2 thrombocytopenia but a higher incidence of grade 0–2 neutropenia." (PMID 40170723, 2025). "In contrast, patients with the UGT1A1*28 wild-type (TA6/6) have a higher incidence of grade 0–2 neutropenia and grade 0–2 leukopenia." (PMID 40170723, 2025). "A high incidence of AEs such as neutropenia, diarrhea, and anemia was observed in patients with altered UGT1A1 haplotypes, especially in those with the homozygous haplotype (28*28) with a difference of 10–20%." (PMID 39518062, 2024). "There was 1 patient with homozygous UGT1A1*6 who experienced febrile neutropenia and 3 patients with heterozygous UGT1A1*6." (PMID 39037543, 2024). "Genetic variants of the phase II gene UDP-glucuronosyltransferase 1A1 (UGT1A1) were clearly linked to severe myelosuppression and neutropenia." (PMID 39456536, 2024). "In our analysis, the heterozygous group had a higher incidence of severe neutropenia and febrile neutropenia than patients with UGT1A1 *1/*1, requiring a further reduction in nal-IRI, even though many of them had received a reduced starting dose of nal-IRI." (PMID 36836140, 2023).